MAFB (MAF bZIP transcription factor B)
Diseases named in the same sentence as MAFB in open-access papers (continued):
Sharing a sentence is not in itself a finding about the gene and the disease.
tumor (continued). "The total tumor weight and size was 2236.80 ± 170.17 mg and 2428.79.80 ± 217.27 mm3 for negative control group and 729.80 ± 178.83 mg and 1029.41 ± 207.85 mm3 for MAFB specific siRNA transfected group, respectively (* p < 0.05)." (PMID 26055874, 2015). "In addition, in the M2a state, MAF bZIP transcription factor B (MAFB) and heat shock transcription factor 1 (HSF1) TFs, whose elevated expression in TAMs associates with more aggressive tumor growth, had significantly upregulated phosphosites." (PMID 41255709, 2025). "Thus, MAFB plays a crucial role in promoting tumor cell proliferation and inhibition of MAFB leads to cell cycle arrest." (PMID 37777749, 2023). "Depletion of MafB/c-Maf could alter the molecular pattern that regulates KC retention and migration, leading to their intratumoral infiltration under the guidance of tumor-enriched chemoattractants." (PMID 36821387, 2023). "Silencing circ_0051079 inhibited tumor growth in vivo via regulating the miR-1286/MAFB axis." (PMID 36153605, 2022). "This research unraveled that circ_0051079 might increase MAFB level by competitively interacting with miR-1286, thereby promoting OS cell progression and tumor growth." (PMID 36153605, 2022). "Additionally, MAFB protein is expressed in the tissue of Dupuytren’s cord, and MAFB and Sox9 form a positive feedback loop that maintains cell stemness and tumor growth in vitro and in vivo." (PMID 35563428, 2022). "Altogether, circ_0051079/miR-1286/MAFB axis regulated OS tumor growth in vivo." (PMID 36153605, 2022). "MAFB is a key regulator of the development of endocrine cells, hematopoietic cells, and the development of the orofacial region in addition to functioning in medullary contexts as a tumor suppressor gene." (PMID 32019513, 2020). "Furthermore, it has been reported that MAFB gene expression promotes cell migration, invasion, and proliferation in vitro and tumor growth in vivo when using mouse xenograft models, in agreement with the oncogenic properties of MAFB." (PMID 32178359, 2020). "Thus, MAFB would be merely overexpressed for its tumor suppressor function to overcome the oncogenic properties of the CdtB." (PMID 32178359, 2020). "Increased MAFB expression was correlated with advanced tumor stages." (PMID 27829226, 2016). "Taken together, these data suggest that SUMOylated MAFB promotes tumor formation in vivo." (PMID 27829226, 2016). "We also assessed MAFB expression in CRC specimens, and analyzed its association with tumor stage." (PMID 27829226, 2016). "In particular, this included genes involved in secretory pathways, lipid and sugar metabolism (such as, UGDH, SORD, GLUD1, ELOVL5, ASCL3, UAP1), but also genes implicated in tumor progression and metastasis with functions in cell survival, proliferation and adhesion (EHF, ELL2, TPD52, MAFB, SGK)." (PMID 21829708, 2011). "The MAFB-WTAP-CD55 axis is identified as a novel and potential therapeutic target to inhibit tumor progression and immune evasion in OC." (PMID 41280929, 2025). "In HCC, all-trans retinoic acid (ATRA) enhances TFPI2 via retinoic acid receptor alpha (RARα), modulated by MAF bZIP transcription factor B (MAFB, activator) and MAFF (repressor), influencing tumor invasion." (PMID 40361374, 2025). "Real-time quantitative polymerase chain reaction (RT-qPCR) was performed to assess MAFB expression in CRC tissues and paired adjacent non-tumor tissues from 61 surgically treated patients." (PMID 27829226, 2016). "However, the role of MAFB in tumor progression remains largely unknown." (PMID 27829226, 2016). "Pro-apoptotic activities have been described for GLIPR1 and MAFB that were upregulated in immortalized keratinocytes and HPV+ tumor cells." (PMID 23702334, 2013). "As for cluster 13, CD68 was strongly expressed in stage I and CD204 in the advanced tumor, but MAFB was not expressed." (PMID 36077342, 2022).
tumor (continued). "The absence of MAFB from lymphatic vessels did not change the weight of tumor-draining lymph nodes or the abundance of migratory dendritic cells arriving in the nodes, suggesting that lymphatic drainage of the tumor bed is similar in Cre− and Cre+ animals." (PMID 32307629, 2020). "Clinical pathological parameters, like age, gender, histological type and tumor location, did not correlate with MAFB level." (PMID 27829226, 2016). "Scramble shRNA (SHC002), MAFB shRNA678, and MAFB shRNA678 plus wild-type MAFB-infected SW1116 cell lines, along with two SW1116 cell lines infected with retrovirus expressing wild-type MAFB or MAFBK32R, were subcutaneously inoculated into nude mice to induce tumor xenografts." (PMID 27829226, 2016). "By contrast, tumor-induced lymphangiogenesis was enhanced in mice lacking lymphatic MAFB." (PMID 32307629, 2020). "In all 6 mice for MAFB specific group, 4 mice could be seen tumors growth after 23 days while there was tumor growth in all negative control group." (PMID 26055874, 2015).
cancer (24 papers, 2016 to 2025). A tumor composed of atypical neoplastic, often pleomorphic cells that invade other tissues. "CdtB-induced MAFB upregulation could be associated with tumorigenesis, as MAFB protein exhibits oncogenic activities and promotes cancer." (PMID 32178359, 2020). "KCs proliferated, infiltrated into tumors, and ingested cancer cells upon BIL-CRISPR–mediated inactivation of MafB/c-Maf." (PMID 36821387, 2023). "ß-catenin, MafB, and WDR77 have all been linked to cancer, and they are important for breast cellular transformation in our Src-inducible model." (PMID 35482762, 2022). "The cancer tissues were immunostained using an anti-MAFB antibody, and the number of MAFB-positive cells relative to the tissue area was counted." (PMID 36077342, 2022). "Compared to CD68 and CD204, MAFB was markedly less expressed in AM and specifically expressed in ML and Mo in all data from normal lung and cancer tissues." (PMID 36077342, 2022). "MAFB is a bona fide oncogene in human cancers that is able to transactivate and transform primary cells." (PMID 32178359, 2020). "We also found copy number loss of cancer genes such as CCNE1, MAF, MAFB, MYC, ZNF479, and MGMT and copy number gain of FOXA2, CDH10, and GPC5 in at least two WDPM cases." (PMID 32545767, 2020). "In this study, we investigated MAFB status in TCGA using the online analysis tool, cBioPortal, and found that MAFB was amplified in a majority of cancer types." (PMID 27829226, 2016). "MAFB and downstream targets of its transcriptional network are now being regarded as predictive biomarkers for certain types of tumors as well as being considered as potential therapeutic targets for cancer treatment." (PMID 40506426, 2025). "Similarly, clinical characteristics related to cancer recurrence, including nodal involvement, lymphatic permeation, and vessel invasion, were lower in tissues with low-MAFB+, while the high-MAFB+ group showed a significant correlation." (PMID 36077342, 2022). "Cancer diagnostic TAM markers, CD68, CD204, CD206, and CD163, are expressed on lung tissue AM; however, the poor MAFB expression on AM might significantly impact the assessment of cancer progression using TAM as an indicator." (PMID 36077342, 2022). "MAFB and GPR68 genes are downregulated interactors of RFX6 that Swiss-Prot associates with cancer." (PMID 34715892, 2021). "Some factors identified (e.g., NF-κB, STAT3, FOS) are known to be involved for transformation in our model, others (e.g., CEBPB, HIF1a, ETS2, FHL2, TCF7L2, and NFE2L2) have been described as oncogenes in other settings, and some proteins (BHLHE40 and MAFB) have not been well linked to cancer." (PMID 29802342, 2018). "When comparing NACT-treated samples with untreated ones in cancer patients the expression of TMEM51, NOTCH1, EEPD1, MAFB, and HLA-DRB5 remained increased in monocytes of treated patients." (PMID 39315092, 2024). "MAFA, MAFB, and MAF are large MAF proteins that have been shown to be oncogenes in tissue cultures, animal models, and human cancer." (PMID 35406570, 2022). "In previous studies, all four genes (ADHFE1, CNRIP1, MAFB, and TNS4) have been reported as cancer-related genes." (PMID 36158666, 2022). "The initial category, containing ANKHD1, ATXN8OS, HSPB8, LSM7, MAFB, and TCTN2, is involved in the direct regulation of cancer cell proliferation, apoptosis, and cancerization." (PMID 34235216, 2021). "The transcription factor, v-maf avian musculoaponeurotic fibrosarcoma oncogene homolog B (MAFB), promotes tumorigenesis in some cancers." (PMID 27829226, 2016). "It has been reported that TFs mediate the functions of lncRNAs in several essential biological processes, such as the lnc-ISIR/IRF3 axis in autoinflammation, the lnc-MAF/MAFB axis in epidermal differentiation, and the lnc-ANRASSF1/PRC2 axis in cancer cell proliferation." (PMID 37107173, 2023).
cancer (continued). "Genes positively correlated with purity showed enrichment in cancer-related pathways and processes such as epithelial-mesenchymal transition (BASP1, COL4A1, THBS2), genes involved in the TNFA signaling via NFKB (SPSB1, SMAD3), and genes upregulated by KRAS activation (CFB, MAFB)." (PMID 37041233, 2023).
infection (13 papers, 2009 to 2025). The state of being infected such as from the introduction of a foreign agent such as serum, vaccine, antigenic substance or organism. "Control mice harboring MafB began to die 4 weeks after infection, and several M. tuberculosis-infected mice died by 10 weeks." (PMID 40906796, 2025). "Regarding MAFB, infection of M-MØ led to diminished MAFB gene expression at early time points but significantly augmented MAFB levels 12 hours and 36 hours after SARS-CoV-2 exposure, whereas MAFB expression raised continuously in SARS-CoV-2–treated GM-MØ." (PMID 37917179, 2023). "Next, we used a lentiviral infection system to establish mouse EC lines in which MafB is stably overexpressed or its endogenous expression suppressed." (PMID 28959057, 2017). "Furthermore, MafB cKO mice showed higher resistance to M. tuberculosis infection than control mice at higher doses of infection." (PMID 40906796, 2025). "Further studies will help elucidate the role of MafB in infectious diseases and may lay the groundwork for novel host-directed therapies against TB and other infections." (PMID 40906796, 2025). "Consistent with reports on patients with TB, we detected high levels of MafB in the lungs of control mice during the active phase of infection, along with poorer IL-12p40 production as compared to cKO mice during early phase of infection, i.e., cytokine restrictions by mycobacteria via MafB." (PMID 40906796, 2025). "However, we can state that the phenotype of the tlr2 mutant, at the infection level, and the level of transcriptional control such as the mentioned effects on regulation of MafB/c-Maf and chemokines shows a clear connection with macrophage chemotaxis." (PMID 31747871, 2019). "The CT genotype of rs2057178 was also associated with decreased expression levels of infection-related gene, suppressor of cytokine signaling 2 (SOCS2), and increased expression levels of v-maf avian musculoaponeurotic fibrosarcoma oncogene homolog B (MAFB)." (PMID 27035414, 2016). "No significant changes in the levels of expression of podocyte marker genes (WT1, PODXL, NPHS1, NPHS2, and MAFB) or for tubular marker genes (SLC3A1 and SLC16A1) were found after infection comparing WT and ACE2 KO kidney organoids." (PMID 35561674, 2022). "This analysis identified a signature for 4 genes, CEBPD (0.93 log2FC), MAFB (0.83 log2FC), IFITM3 (0.55 log2FC), and LGALS1 (−0.53 log2FC), that was markedly enriched in CD14 monocytes in patients who ultimately survived infection." (PMID 35169146, 2022). "Other transcripts that we previously reported as being β-cell specific, including PCSK1 and MAFB, and GLIS3 and CASR, all decreased with infection." (PMID 32093375, 2020). "Transduction and infection experiments both showed that exposure to CDT, via the CdtB subunit, promotes the expression of MAFB protein in intestinal and hepatic cell lines." (PMID 32178359, 2020). "MAFB suppression was detected in established T. annulata infected cell-lines but not during the first 3 days of infection." (PMID 19303416, 2009). "Alternatively, the mechanism of repression may not be fully activated until a later stage of infection, when MAFB is suppressed." (PMID 19303416, 2009).
infectious disease (4 papers, 2016 to 2025). A disorder directly resulting from the presence and activity of a microbial, viral, or parasitic agent in humans. "More importantly, v-maf avian musculoaponeurotic fibrosarcoma oncogene homolog B (MAFB), suppressor of cytokine signaling 2 (SOCS2) were found to be associated with SNP rs2057178 in infectious diseases." (PMID 27035414, 2016). "Thus, MafB potentially contributes to diverse intracellular activities involving IRF and Ets family cognates involved in various autoimmune and infectious diseases." (PMID 40906796, 2025). "MAF BZIP Transcription Factor B (MAFB), a gene highly upregulated in the temporal lobe of the male macaques, has been previously reported to play a sex-specific role in severe SARS-CoV-2 infectious disease (COVID) 32,33." (PMID 38045237, 2023).
adenocarcinoma (2 papers, 2017 to 2022). A common cancer characterized by the presence of malignant glandular cells. "Most of the patients with stage I adenocarcinoma were grouped into the low-MAFB+ (stage I: stage III, 24:6), while a significant number of patients with stage III adenocarcinoma were grouped into the high-MAFB+ group (stage I:stage III, 3:28, p < 0.01)." (PMID 36077342, 2022).
immune disorders (2 papers, 2020 to 2023). "MafB was also implicated in immune disorders as it regulates macrophage apoptosis, phagocytosis and the complement system." (PMID 37845329, 2023). "Our findings suggest that strategies elevating MafB may be effective to treat immune disorders due to excessive activation of the NLRP3 inflammasome." (PMID 37845329, 2023).
colorectal (1 paper, 2022). "Just like MAFB, no previous studies have investigated the roles of aberrant methylation of TNS4 in colorectal carcinogenesis." (PMID 36158666, 2022).
head and neck tumors (1 paper, 2019). "Among the most impressive differences in TF activity, head and neck tumors display lower activities of FEV, TFAP2B and GATA2 and higher activities of TFEC, LEF1, and MAFB compared to SDHD-null tumors of other anatomical locations." (PMID 31234811, 2019).
hematological cancer (1 paper, 2025). "In this review, we summarize current knowledge on both physiological and pathological roles of MAFB and highlight the impact of its deregulation on hematological cancer initiation and progression." (PMID 40506426, 2025).
hematological diseases (1 paper, 2025). "Dysregulation of MAFB expression or function has been implicated in several pathological conditions, including hematological malignancies and metabolic disorders." (PMID 40506426, 2025).
respiratory diseases (1 paper, 2013). "Furthermore, the MSR-DN MafB TG mouse model has the potential to contribute to our understanding of the pathogenesis of respiratory diseases including COPD." (PMID 24040127, 2013).
MAFB also shares sentences with these, for which no sentence is quoted: coronary artery disease (3 papers); acute myeloid leukemia (2); Cerebral ischemia (2); allergic asthma (1); arteriosclerosis (1); Arthritis (1); Ayme-Gripp syndrome (1); Central apnea (1); chronic kidney disease (1); Cirrhosis (1); cognitive decline (1); colorectal adenocarcinoma (1); diabetic angiopathy (1); diabetic retinopathy (1); diffuse large B-cell lymphoma (1); Dupuytren disease (1); dyslipidemia (1); endometrial cancer (1); fibrosis (1); genetic disease (1); glioma (1); glomerulonephritis (1); Hypertension (1); interstitial lung disease (1); ischemia (1); islet cell tumors (1); Lipedema (1); lymphedema (1); mastitis (1); metabolic disorders (1).
A further 14 diseases each share a sentence with MAFB in 1 paper.